COPS2 (COP9 signalosome subunit 2)
Description:
Essential component of the COP9 signalosome complex (CSN), a complex involved in various cellular and developmental processes. The CSN complex is an essential regulator of the ubiquitin (Ubl) conjugation pathway by mediating the deneddylation of the cullin subunits of SCF-type E3 ligase complexes, leading to decrease the Ubl ligase activity of SCF-type complexes such as SCF, CSA or DDB2. Involved in early stage of neuronal differentiation via its interaction with NIF3L1.
Synonyms: SGN2; CSN2; TRIP15; ALIEN
Tractability: PROTAC: ubiquitination databases record sites on it; its protein half-life has been measured.
Gene: Protein-coding gene on chromosome 15 (49,106,068 to 49,155,661, reverse strand). Ensembl gene ENSG00000166200.
Subcellular location: Cytoplasm; Nucleus
Subcellular location (Human Protein Atlas): Vesicles; Cytokinetic bridge
Pathways (Reactome):
DNA Repair: DNA Damage Recognition in GG-NER; Formation of TC-NER Pre-Incision Complex
Metabolism of proteins: Neddylation
Signal Transduction: RHOBTB1 GTPase cycle
Vesicle-mediated transport: Cargo recognition for clathrin-mediated endocytosis
Gene Ontology:
Molecular function: protein binding
Biological process: protein deneddylation; protein phosphorylation; negative regulation of transcription by RNA polymerase II; protein neddylation; regulation of protein neddylation; signal transduction; transcription by RNA polymerase II; neuron differentiation
Cellular component: COP9 signalosome; cytoplasm; intercellular bridge; nucleus; cytosol; nucleoplasm; protein-containing complex
Genetic constraint (gnomAD): Loss-of-function variants: 0 observed, 21.67 expected, observed/expected ratio (o/e) 0, 90% interval 0 to 0.14. The upper end of that interval is the gene's LOEUF score, 0.14, which puts it in group 1 of 6, group 1 being the genes least tolerant of losing a copy. Missense variants: 99 observed, 225.45 expected, observed/expected ratio (o/e) 0.44, 90% interval 0.37 to 0.52. Synonymous variants: 79 observed, 76.24 expected, observed/expected ratio (o/e) 1.04, 90% interval 0.86 to 1.25.
Homologues: Orthologues: chimpanzee COPS2 (100% identical), guinea pig COPS2 (100% identical), macaque COPS2 (100% identical), mouse Cops2 (100% identical), rabbit COPS2 (100% identical), rat Cops2 (100% identical), tropical clawed frog cops2 (99% identical), zebrafish cops2 (99% identical), pig COPS2 (97% identical), dog COPS2 (96% identical), Drosophila melanogaster alien (84% identical), Caenorhabditis elegans csn-2 (63% identical). Paralogues in human: PSMD11 (25% identical).
Diseases named in the same sentence as COPS2 in open-access papers:
COPS2 is named in the same sentence as 14 diseases in open-access papers, as found by Europe PMC text mining. Sharing a sentence is not in itself a finding about the gene and the disease. The quoted sentences say what the papers report.
adenoma (1 paper, 2015). A neoplasm arising from the epithelium. "Both UCP2 and COPS2 were significantly decreased in adenomas and carcinomas with a 13q gain compared to those without." (PMID 26148070, 2015). "The comparison of adenomas without 13q gain to carcinomas with 13q gain, showed for both UCP2 and COPS2 significantly decreased expression in carcinomas with 13q gain." (PMID 26148070, 2015).
bladder cancer (1 paper, 2025). "The analysis revealed that UBE2D3 and COPS2 are highly expressed in seven different bladder cancer cell types, whereas HIF3A and CUL1 are expressed at low levels in the same cell clusters." (PMID 40524221, 2025). "Further multivariate Cox regression confirmed that HIF3A, DDB1, COPS2, and UBE2D3 may independently indicate bladder cancer prognosis." (PMID 40524221, 2025).
colorectal adenoma (1 paper, 2024). An adenoma that arises from the colon or rectum. "Carvalho and colleagues identified COPS2 as a possible candidate target gene for miR-15a-3p to inhibit the progression of colorectal adenoma." (PMID 38466642, 2024).
gastric cancer (1 paper, 2025). A primary or metastatic malignant neoplasm involving the stomach. "Similarly, diminished expression of DDB1 in pancreatic cancer is linked to improved patient survival, and high levels of COPS2 have been shown to predict the occurrence of gastric cancer." (PMID 40524221, 2025).
hypothyroidism (1 paper, 2012). Abnormally low levels of thyroid hormone. "Her deletion comprises 19 genes and predicted genes including FBN1, besides SEMA6D and COPS2 that may have contributed to the intellectual deficit and hypothyroidism, respectively." (PMID 22260333, 2012).
melanoma (1 paper, 2021). A malignant, usually aggressive tumor composed of atypical, neoplastic melanocytes. "In the case of melanoma (MEL), high novelty targets are SPPL2A, CHL1, AP4E1, SECISBP2L, and COPS2." (PMID 34570764, 2021).
ovarian carcinoma (1 paper, 2012). A malignant neoplasm originating from the surface ovarian epithelium.
Sepsis (1 paper, 2022). Sepsis is defined as life-threatening organ dysfunction caused by a dysregulated host response to infection. "COPS2 is an important component of the COP9 signalosome complex, which contributes to various cellular processes, the regulation of the ubiquitin conjugation pathway, and also development of sepsis in patients with TNF-α rs1800629 A variant." (PMID 35041720, 2022).
tumor (6 papers, 2015 to 2025). "For instance, COPS2 is considered a putative tumor suppressor gene." (PMID 38466642, 2024). "Also COPS2 was described as a putative tumour suppressor gene in a panel of different cancer types, where loss-of-function showed partial bypass of cellular senescence." (PMID 26148070, 2015). "The present data indicate that UCP2, and potentially also COPS2, may function as tumour suppressors in CRC." (PMID 26148070, 2015). "Similarly, knockout of COPS2 or BRIP1 achieved significant reduction of tumor burden." (PMID 36333584, 2022). "Notably, transcriptomic data and RTqPCR results demonstrated that while PUM2 and HIF3A were highly expressed in normal tissues, DDB1 showed increased expression in tumor tissues, with CUL1, COPS2, and UBE2D3 remaining unchanged." (PMID 40524221, 2025). "Transcriptomic data and RT-qPCR findings indicated that PUM2 and HIF3A exhibited high expression levels in normal tissues, while DDB1 showed increased expression in tumor tissues; no significant changes were observed for CUL1, COPS2, and UBE2D3." (PMID 40524221, 2025).
cancer (3 papers, 2015 to 2022). A tumor composed of atypical neoplastic, often pleomorphic cells that invade other tissues. "The cancer susceptibility gene BRIP1, as well as COPS2, part of the COP9 signalosome, have both been implicated in DNA damage repair, and were associated with treatment failure and dismal prognosis." (PMID 36333584, 2022). "Thus, it is plausible that 2–3 years before the diagnosis of cancer, PCA3-shRNA2 expression is not elevated, as the target mRNAs (such as COPS2 and SOX11) do not have, as yet, altered function in the prostate." (PMID 28380027, 2017).
infection (1 paper, 2017). The state of being infected such as from the introduction of a foreign agent such as serum, vaccine, antigenic substance or organism. "However, the overexpression of COPS2 in CEF cells is not consistent in infection with all IAV subtypes." (PMID 29104227, 2017).
COPS2 also shares sentences with these, for which no sentence is quoted: Alzheimer disease (1 paper); pancreatic cancer (1); Zinc deficiency (1).